IL27 (interleukin 27)
Diseases named in the same sentence as IL27 in open-access papers (continued):
Sharing a sentence is not in itself a finding about the gene and the disease.
tumor (continued). "Indeed, cytokines such as IFN-γ, IL-27, IL-23, IL-12, and IL-2 have tumor suppressor functions, whereas pro-inflammatory cytokines, including IL-1, IL-6, and tumor necrosis factor-α, have tumor-promoting." (PMID 37046658, 2023). "Furthermore, we found that the immunoregulatory cytokine, IL-27 enhanced protection against tumor growth in a dose-dependent manner when combined with either LyUV or γ-irradiated whole tumor cell vaccine preparations." (PMID 35529885, 2022). "The IL-12 family of cytokines consists of IL-12, IL-23, IL-27, and IL-35, with IL-12, IL-23, and IL-27 being mainly produced by macrophages and dendritic cells, while IL-35 is predominantly secreted by regulatory T cells but can also be expressed by tumor cells." (PMID 36428508, 2022). "The levels of IL-27 may be an important factor to consider where higher amounts may reduce the potential for an anti-tumor immune response to ensue in a prophylactic model." (PMID 35529885, 2022). "NK cells can also respond to IL-27 and promote effector cell function in viral and tumor models." (PMID 35529885, 2022). "Both IL-9 and IL-27 are pleiotropic cytokines that could induce innate/adaptive immune responses and promote tumor cell apoptosis by enhancing the action of cytotoxic T lymphocytes." (PMID 36615662, 2022). "Therefore, IL-27 shows promise in enhancing anti-tumor responses but requires further investigation into the mechanisms that are responsible for its pleiotropic effects." (PMID 35529885, 2022). "Consequently, the IL-27 signaling pattern is a natural antagonist of IL-6 oncogenic signaling, leading to the activation of proinflammatory genes and the mediation of tumor-suppressive signals." (PMID 35200430, 2022). "Then, IL27 expression was compared between tumor and normal tissues in pan-cancer." (PMID 36713514, 2022). "Other aspects of the tumor-controlling capacity of IL-27, such as its ability to induce the proliferation of naïve CD8+ T cells or the differentiation of CTLs, seem to be independent of the presence of the transcription factor T-bet, which crucially controls the fate of Th1 cells and CTLs." (PMID 36428508, 2022). "In addition to reengineering tumor microenvironment, IL27 also directly affects malignant progression of cancer cells." (PMID 36713514, 2022). "Indeed, IL-27 is mainly produced by myelomonocytic cells, while IL-6 can be secreted by several other cell types, including T lymphocytes and tumor cells." (PMID 34439164, 2021). "Moreover, IL-27 signaling on tumor cells activated STAT1; upregulated the expression of PD-L1 and production of IL-10, TGF-β and IDO; and downregulated MHCI expression." (PMID 33418929, 2021). "Given the ability of IL-27 to regulate both pro-tumorigenic and anti-tumorigenic responses, the choice of the augmentation or blockade of IL-27 should be carefully evaluated given the tumor type and the immune contexture." (PMID 33418929, 2021). "IL27 has been shown to be an immune-enhancing cytokine with potent anti-tumor activity." (PMID 33859739, 2021). "Furthermore, IL-27 secreted by tumor-infiltrated neutrophils upregulated CD39 expression and enhanced the immune suppressive capacity of CD163+ macrophages." (PMID 33418929, 2021). "Considering that both IL‐6 and IL‐27 contribute to tumour progression through JAK/STAT3 signalling pathway, we next elucidated whether CD63 regulated the activation of signal transducer and activator of transcription‐3 (STAT3) by Western blot analysis." (PMID 33277798, 2021). "Thus, our results strongly suggested IL27 can play a role in distinct hot/cold tumor states and the resulting therapeutic response, which was confirmed by subsequent analysis." (PMID 34733272, 2021). "Moreover, tumor volume for the control group was observed to be significantly larger than that in IL27 overexpressing group in a previously reported study." (PMID 34733272, 2021).
tumor (continued). "First, IL27 could drive effector T cell infiltration and activation, and second, IL27 could trigger tumor cell pyroptosis, autophagy and apoptosis." (PMID 34733272, 2021). "We hypothesized that addition of IL-18, which can induce the proliferation of several immune effector cells through inducing IFNγ could synergize with IL-27 to enhance tumor growth control." (PMID 34209203, 2021). "Since tumor-infiltrating immune cells express functional IL-27R, harnessing the ability of IL-27 to stimulate antitumor activity in immune cells could be an effective approach." (PMID 34045653, 2021). "IL-27 signaling in innate and adaptive immune cells as well as in cancer cells regulates the expression of distinct key molecules important for the activation of immune responses in the tumor milieu." (PMID 33418929, 2021). "The role of IL-27 in NK cell-mediated anti-tumor immunity has been defined." (PMID 34440725, 2021). "In one study, the role of IL-27, another anti-inflammatory tumour suppressor, was elucidated." (PMID 34336101, 2021). "IL-27 showed a significant prediction of recurrence, analyzed by Kaplan–Meier analysis (p = 0.026) and multivariate Cox regression analysis, with covariates being age, gender and tumor size (HR 6.89; CI 1.56–30.4; p = 0.011)." (PMID 32621022, 2021). "Another anti-inflammatory cytokine, IL-27, is known to act as a tumour suppressor." (PMID 34336101, 2021). "Whereas IL-6 has mainly pro-tumor activities, IL-27 may have a dual biological role in different cancers." (PMID 34439164, 2021). "IL-27 is also able to directly act on tumor cells to perform antitumor functions." (PMID 34045653, 2021). "Given an established role for IL-18 and IL-27 in stimulating optimal IFNγ production and Th1 responses, our data suggest that increased tumor burden in the mice receiving AdIL-17A-transduced 4T1 cells could be due to the progressive loss of Th1 immunity." (PMID 32770025, 2020). "IL-27 is an anti-inflammatory cytokine that has been shown to have potent anti-tumor activity." (PMID 32292786, 2020). "In addition, AAV vectors expressing antitumoral cytokines, such as IL-12 or IL-27 have been successfully used in tumor preclinical models." (PMID 33276580, 2020). "AAV–IL-27 intra-tumor administration resulted in IL-27 production in tumors." (PMID 32292786, 2020). "The targeted IL-27 appeared to modulate several changes that would be consistent with an anti-tumor effect, including upregulation in the IFN and Interferon regulatory factor (IRF) signaling, oxidative phosphorylation, JAK/STAT signaling, and eukaryotic initiation factor 2 (EIF2) signaling." (PMID 32046108, 2020). "The receptor for IL-27, a heterodimer composed of IL-27 receptor alpha (IL-27RA) and glycoprotein 130 (gp130) subunits, is highly expressed in lymphoid organs, bone, normal and tumor epithelial cells, melanoma, and leukemia." (PMID 32046108, 2020). "Importantly, we were able to demonstrate an IL-27-dependent higher cytotoxicity of NK cells toward PyMT tumor cells." (PMID 33014872, 2020). "We hypothesized that targeting the cytokine to tumor tissue by utilizing peptides that could bind receptors upregulated in tumor cells, such as the interleukin-6 receptor (IL-6Rα), could help augment IL-27 bioactivity." (PMID 32046108, 2020). "IL-27 is known to induce T cell expression of PD-L1, and PD-L1-PD-1 interaction among T cells may inhibit T cell effector functions thereby limiting IL-27-mediated anti-tumor efficacy." (PMID 32292786, 2020). "Finally, we found that co-culture of tumor-antigen P1A-specific P1CTL cells with IL-27 in vitro resulted in significant upregulation of CXCR3 in P1CTL cells, suggesting that IL-27 can directly induce CXCR3 in tumor-specific T cells." (PMID 32292786, 2020). "Competition between IL-27, IL-30, and IL-35 for receptor subunits may affect the overall balance of pro- vs. anti-tumor effects of these cytokines." (PMID 31681561, 2019).
tumor (continued). "Recently, both anti-tumor and pro-tumor roles have been attributed to IL-27." (PMID 31681561, 2019). "In humans, the impact of IL-27 on NK cells in a tumor setting needs to be further investigated, in particular how IL-27 could simultaneously coordinate NK cell activity and tumor cell death." (PMID 31681561, 2019). "This suggests that IL-27 may influence the macrophage phenotype within the TME leading to modulation of tumor growth." (PMID 31681561, 2019). "Taken together, IL-27 serves as an important modulating cytokine in the TME that can be used to either enhance the activation of potent anti-tumor immune cells, directly inhibiting cancer cell proliferation and angiogenesis or promote tumor development and survival." (PMID 31681561, 2019). "IL-27 and has been shown to modulate NK cells anti-tumor cytotoxicity responses." (PMID 30899058, 2019). "We show that rather depletion of IL-27 signaling disturbs tumor angiogenesis." (PMID 31637217, 2019). "Differential effects of IFN-g, IL-1a, and IL-27 on individual tumor cell lines were not due to PDL1 promoter polymorphisms." (PMID 31730010, 2019). "Additionally, IL-27 can promote anti-tumor immune responses by altering development and activation of various T cell subsets and NK cells." (PMID 31681561, 2019). "IL-27 can directly suppress tumorigenesis by interacting with cancer cells, or indirectly by stimulating different subsets of immune cells resulting in their activation against a developing tumor." (PMID 31681561, 2019). "In addition to preventing IL-27 signaling, IL-30 can limit IL-12-induced Th1 differentiation, thus serving as an additional contributing factor to promoting tumor growth." (PMID 31681561, 2019). "IL-27 directly induces apoptosis of cancer cells resulting in an anti-tumor immune response." (PMID 31681561, 2019). "The ability of IL-27 to upregulate immune checkpoint ligands on tumor endothelium may significantly differ among patients." (PMID 31185596, 2019). "There is evidence that combining IL-27 with an immune checkpoint inhibitor may enhance an immune response while simultaneously promoting the anti-tumor effects of IL-27, but further investigation is needed for these combination therapies." (PMID 31681561, 2019). "In all studies, it has been proposed that IL-27 has tumor suppressing effects on NSCLCs." (PMID 30581461, 2018). "IL-27 shows an effect of anti-tumor immunity as a possible therapeutic target for cancer." (PMID 30483251, 2018). "IL-27 and the tumor microenvironment were also involved in modulating Tim-3 expression." (PMID 30687334, 2018). "IL-27 has been shown to have both tumor promoting and suppressing functions." (PMID 30581461, 2018). "Reports in KO models suggest a role for endogenous IL-27 in the control of tumor growth." (PMID 28255204, 2017). "Although IL-27 has shown well-documented antitumor activity in several experimental models, a few reports suggest that it may also have potential tumor-promoting effects." (PMID 28255204, 2017). "As for IFN-γ the IL-27 capability of upregulating immune checkpoint ligands on tumor endothelium, may greatly vary among patients." (PMID 28456791, 2017). "Besides its effects on HLA class-I induction in human cancer cells, IL-27 has shown antitumor activity in several tumor models in vitro and in vivo." (PMID 28255204, 2017). "IL-27 may also exert direct anti-tumor effects through the inhibition of angiogenesis and neoplastic cell proliferation in different cancers including acute myeloid leukemia, prostate cancer, and melanoma." (PMID 29020964, 2017). "Several reports indicate that IL-27 may exert direct inhibitory effects on tumor cells expressing the WSX1/gp130 receptor." (PMID 28255204, 2017). "Nonetheless, the effects of IL-27 on the immune response may be dual, resulting in tumor promoting effects in vivo, as suggested by increased IL-27 expression in some human cancers." (PMID 28255204, 2017).
tumor (continued). "In view of the defective expression of HLA class I molecules in SCLC, we tested whether IL-27 could up-regulate membrane HLA, as recently reported in other tumor cell types." (PMID 29020964, 2017). "In the past decade, IL-27 has attracted considerable interest as a potent antitumor cytokine via CD8+ T cell-dependent tumor rejection, limiting the inducible Treg (iTreg) or Treg population, enhancing NK cell response, and inhibiting angiogenesis and tumor cell proliferation." (PMID 27247488, 2016). "This aspect seemed relevant as surface expression of HLA class I on cancer cells is crucial for CTL-mediated anti-tumor immunity and its up-regulation could be involved in the anti-tumor effects of IL-27." (PMID 27683036, 2016). "This biological activity could contribute to the anti-tumor effects of IL-27, which is mainly related to the induction of Th1 and CTL responses, in pre-clinical models." (PMID 27683036, 2016). "Notwithstanding these immune regulatory effects, IL-27 has shown anti-tumor activity in several cancer models in vitro and in vivo, not only through the activation of anti-tumor immune responses but also through direct effects on the tumor cells." (PMID 27683036, 2016). "IL-27 displays antitumor activity in vivo through multiple mechanisms, including antitumor immunity and antiangiogenesis activity, depending on the characteristics of tumor models." (PMID 27119567, 2016). "Indeed, IL-27 pre-treatment of HLA class Ilow tumor cells inhibited the activation of allogeneic NK cells, as detected by functional assays." (PMID 27683036, 2016). "Importantly, we found that IL-27 induced HLA class I molecule expression in human cancer cells of different histotypes, including tumor cells showing very low expression." (PMID 27683036, 2016). "On the other hand, endogenous IL27 has been related to features of tumor progression." (PMID 27738312, 2016). "Also, it has been proposed that IL-27 enhances the survival of anti-tumor CTLs and induces a peculiar stem cell-like Tc1 effector phenotype, characterized by the expression of T-bet, Eomes, Bcl1, Sca1 and IL-10." (PMID 27683036, 2016). "Opposite to the induction of protective T cell anti-tumor immunity, the IL-27-mediated induction of HLA class I molecules may result in tumor cell protection from NK cell-mediated lysis as pointed out by network analysis." (PMID 27683036, 2016). "However, previous findings suggest a dual role of IL-27 in the anti-tumor immune response, which should be taken into account in the design of IL-27-based immunotherapies." (PMID 27683036, 2016). "Thus, our findings suggest that the MAPK/ERK signaling cascade is primarily required for IL-27-induced tumor growth and survival." (PMID 27119567, 2016). "Another effect of IL-27 that may contribute to its anti-viral and anti-tumor activities is related to the induction of HLA class I expression." (PMID 27683036, 2016). "Also, IL-27 produced by DCs upon recognition of apoptotic tumor cells induces expression of immune-suppressive CD39 ecto-ATPase on Treg cells, which inhibits CTL responses." (PMID 27683036, 2016). "To further understand whether IL27 can promote tumor incidence in the skin, we administered plasmid DNA into the rear tibialis muscle followed by electroporation as a gene delivery method." (PMID 27738312, 2016). "We next investigated whether IL-27 regulated, in both lines, sets of genes shaping tumor malignancy and specifically related to angiogenesis, stemness and invasiveness." (PMID 25638163, 2015). "Collectively these data suggest that the combination of IL-27 with inhibitors of IDO or PD-L1/PD-1 should enhance its anti-tumor effects and may be exploited in pre-clinical models of cancer immunotherapy." (PMID 26657115, 2015). "In conclusion, the net effect of IL-27 as an anti-tumor agent may depend on the balance of multiple factors." (PMID 26657115, 2015). "Myeloablation of tumor-bearing hosts mostly abolished IL-27's antitumor effects." (PMID 25638163, 2015).
tumor (continued). "Also, a number of in vivo studies exist that implicates IL-27 in the regulation of anti-tumor immunity mediated by CD8+ T cells." (PMID 25633106, 2015). "On the other hand, IL-27 has shown anti-tumor activity in different cancer models in vitro and in vivo, through different mechanisms, including direct effects on tumor cells or activation of an anti-tumor immune response." (PMID 26657115, 2015). "Tumor responsiveness to IL-27, however, is the prerequisite for its entry into clinical trials." (PMID 25638163, 2015). "IL-12 and IL-27 seem to have antagonistic roles with IL-23 in tumor site." (PMID 25031487, 2014). "Such IL-27 anti-tumor activity was related to the direct inhibition of PC3 angiogenic program towards an anti-angiogenic phenotype that allows consistent subversion of the host derived microvascular network resulting in a heavily compromised architecture and rarefied endothelial branching." (PMID 24681516, 2014). "In recent years, Interleukin-27 has been considered as a potential anti-tumor agent." (PMID 24633175, 2014). "We, thus, investigated whether IL-27 may function as anti-tumor agent in human (h) PCa and analyzed the rationale for its clinical application." (PMID 24681516, 2014). "Many studies suggest a role of IL-27 in enhancing anti-tumor CD8+ T cell responses." (PMID 24633175, 2014). "As tumor cells exacerbate the pro-inflammatory and Th2 responses for their survival, the immune system reacts by up-regulating anti-inflammatory and Th1 responses such as IL-27 synthesis." (PMID 25031487, 2014). "J558-IL-27 tumor cells with moderate production rate of IL-27." (PMID 24633175, 2014). "It is concluded that the overexpression of IL-23 and IL-27 gene transcripts may be an immune response to the tumor development." (PMID 25031487, 2014). "IL-27 displays anti-tumor activity via different mechanisms." (PMID 24681516, 2014). "Since IL-27 revealed anti-tumor effects in a variety of tumor models, we assessed whether IL-27 may function as anti-tumor agent against human (h) PCa." (PMID 24681516, 2014). "Recent experiments in vitro and in vivo have shown that cancer cells transfected with IL-27 activate CD8+ T cells to promote the secretion of anti-tumor cytokines Interleukin-10, although, at the same time, IL-27 inhibits the secretion of Interferon- by CD8+ T cells." (PMID 24633175, 2014). "However, since IL-12 is excessively toxic, the cytokine IL-27, which is a less toxic member of the IL-12 family, has been considered as a possible replacement of IL-12 as anti-tumor agent." (PMID 24633175, 2014). "Regulatory T cells promote tumor growth and are inhibited by IL-27." (PMID 24633175, 2014). "To determine whether hPCa patients could benefit from IL-27's anti-tumor effects, we next immunohistochemically evaluated expression and distribution of IL-27R in prostate tissue sections from PCa patients following radical prostatectomy (RP)." (PMID 24681516, 2014). "This vast category of patients may never need treatment and only an “active surveillance” is currently recommended by urologists, while IL-27 based immunotherapy could be an effective weapon against unexpected tumor progression." (PMID 24681516, 2014). "However, the TRAIL expression level induced by IL-27 and poly(I:C) seems to vary among three tumor cell lines; highest in SK-MEL-37 and lowest in SK-MEL-12 cells." (PMID 24155891, 2013). "IL-27 mediated inhibition of angiogenesis is a known anti-tumor mechanism in various malignancies." (PMID 24274066, 2013). "Finally, in vivo antitumor effects of IL-27 or the combination of IL-27 and poly(I:C) were examined using a tumor xenograft mouse model in immunodeficient NOD/SCID mice." (PMID 24155891, 2013). "Taken together, these properties of IL-27 suggest it could enhance anti-tumor immunity by both promoting beneficial TH1 responses and suppressing Treg activity." (PMID 23554861, 2013). "The anti-angiogenesis properties of IL-27 in tumor models have been described previously." (PMID 24274066, 2013).